HDAC7 (histone deacetylase 7)
Diseases named in the same sentence as HDAC7 in open-access papers (continued):
Sharing a sentence is not in itself a finding about the gene and the disease.
lung carcinoma (11 papers, 2017 to 2025). "High HDAC7 is also linked with advanced cancers and leads to a poor prognosis, which has been validated in breast and lung cancers." (PMID 36653340, 2023). "HDAC7 overexpression contributes to migration and is linked with a poor prognosis in lung cancer, nasopharyngeal carcinoma, and esophageal squamous cell carcinoma (ESCC)." (PMID 36653340, 2023). "Higher HDAC7 protein level is observed in ~44% of human lung cancer samples and higher HDAC7 mRNA level is associated with poor prognosis of lung cancer patients." (PMID 29126425, 2017). "Here we show that mouse Hdac7 mutation suppresses lung tumor development in vivo and HDAC7 silencing in human lung cancer cell lines inhibits their proliferation in vitro." (PMID 29126425, 2017). "Although a few previous studies have indicated that HDAC7 was involved in tumorigenesis and cell growth in lung cancer, the expression and mechanisms underlying the oncogenic function in NSCLC remains largely unknown." (PMID 35277183, 2022). "The last member of IIa class—HDAC7 is associated mainly with lung cancer." (PMID 30691229, 2019). "HDAC7 belongs to class IIa HDACs and contributes in the progression of breast cancer, nasopharyngeal cancer and lung cancer." (PMID 39431349, 2024). "A recent study on lung cancer also validated HDAC7 contributed to the proliferation of cancer cells by deacetylating β-catenin and further activating FGF18 expression." (PMID 36653340, 2023). "Recent studies on lung cancer have also shown that HDAC7 has positive effects on tumorigenesis and cell growth via inhibition of Stat3 and plakoglobin." (PMID 35277183, 2022). "Our study shows that reduction of Hdac7 expression in mice results in a decreased proliferation and increased apoptosis of mouse lung cancer cells." (PMID 29126425, 2017). "Hdac7+/−/K-Ras mice and HDAC7-depleted human lung cancer cell lines were used as models for studying the function of Hdac7 gene in lung cancer." (PMID 29126425, 2017). "We have also observed higher HDAC7 protein level in ~ 44% human lung tumor samples and found that high HDAC7 mRNA level in human lung cancer is correlated to poor prognosis." (PMID 29126425, 2017). "Kaplan-Meier survival analysis was performed to explore the relationship between HDAC7 expression and prognosis of human lung cancers." (PMID 29126425, 2017). "Annexin V assay showed that HDAC7 knockdown resulted in significant enhanced apoptosis of human lung cancer cells." (PMID 29126425, 2017). "Then, Hdac7+/− mice were crossed with K-Ras transgenic mice, the most frequently used mouse model for lung cancer." (PMID 29126425, 2017). "To further investigate the effects of HDAC7 on human lung cancer, we examined HDAC7 protein level in 33 human lung tumors." (PMID 29126425, 2017). "Taken together, these data strongly suggest that Hdac7 mutant can inhibit mouse lung cancer via attenuating cell proliferation and promoting apoptosis." (PMID 29126425, 2017). "To investigate the role of Hdac7 in lung cancer, we first verified Hdac7 expression in wt and Hdac7+/− mouse lung tissues." (PMID 29126425, 2017). "This notion is supported by our observation that the expressions of cyclin D and cyclin E were significantly decreased in both lung tumors from Hdac7+/−/K-Ras mice and HDAC7-depleted human lung cancer cell line H1299." (PMID 29126425, 2017). "Collectively, these results suggest that up-regulation of HDAC7 expression function as an oncogenic factor for human lung cancer development." (PMID 29126425, 2017). "Thus, HDAC7 likely supports the development and progression of lung cancer by multiple mechanisms in various cell types." (PMID 35303381, 2023). "Inhibition of HDAC7 results in restraining of lung cancer development." (PMID 30691229, 2019). "To verify if STAT3 also plays a role in human tumor cell growth regulated by HDAC7, we tested whether expression of dnStat3 was able to rescue the growth suppression mediated by HDAC7 depletion in human lung cancer cell lines." (PMID 29126425, 2017).
lung carcinoma (continued). "Since in vivo study demonstrates that HDAC7 functions as an oncogenic factor in mouse lung cancer, we further reasoned that reduction of HDAC7 expression in human lung cancer cells could inhibit their growth." (PMID 29126425, 2017). "Here we report that Hdac7 functions as an oncogene in lung cancer." (PMID 29126425, 2017). "However, low HDAC7 expression was also observed in 75% of 28 pro-B-ALL samples and reported to be associated poor prognosis of lung cancer patients." (PMID 29126425, 2017). "We found that in the Lenti-Cre infected group, Hdac7 mutant dramatically inhibited lung cancer development, however, in Lenti-Cre-2A-dnStat3 infected group, neither tumor number on lung surface nor tumor burden were significantly different between Hdac7+/−/K-Ras mice and control K-Ras mice." (PMID 29126425, 2017). "To test our hypothesis, we first evaluated STAT3 acetylation status in both lung tumors from Hdac7+/−/K-Ras mice and HDAC7-depleted human lung cancer cell lines." (PMID 29126425, 2017). "Our study suggests that Hdac7 promotes lung tumorigenesis by inhibiting Stat3 activation via deacetylating Stat3 and may shed a light on the design of new therapeutic strategies for human lung cancer." (PMID 29126425, 2017). "Our study showed that not only exogenous Stat3 and Hdac7 proteins expressed in 293T cells were co-immunoprecipitated reciprocally, but also endogenous STAT3 and HDAC7 proteins in human lung cancer cells and mouse lung tumors from control K-Ras mice." (PMID 29126425, 2017). "However, our immunoblotting analysis showed that the expression of JAK1, JAK2 and PKC was not significantly altered when HDAC7 expression was depleted in human lung cancer cell line H1299." (PMID 29126425, 2017).
ovarian carcinoma (11 papers, 2017 to 2024). A malignant neoplasm originating from the surface ovarian epithelium. "Next, we rechecked the association between HDAC7 expression and ovarian cancer patients' survival by using Kaplan–Meier plotter database, and found that HDAC7 expression is associated with poor survival in ovarian cancer patients." (PMID 39431349, 2024). "In conclusion, we elucidated the underlying molecular mechanism of HDAC7 in the progression of ovarian cancer growth via enhancing the levels of p‐AKT and p‐mTOR." (PMID 39431349, 2024). "We found that HDAC7 expression is associated with poor prognosis of ovarian cancer patients and induces cell proliferation and invasion by activating AKT/mTOR pathway." (PMID 39431349, 2024). "What's more, mut‐activated AKT in ovarian cancer, can rescued cell proliferation and invasion which cause by HDAC7 inhibition." (PMID 39431349, 2024). "The observed upregulation of HDAC7 in tumour tissues and its association with poor prognosis in patients with ovarian cancer led us to postulate that HDAC7 may act as tumour promoter." (PMID 39431349, 2024). "In addition, we also performed Kaplan–Meier survival analysis to investigate the association between HDAC7 expression and clinical prognosis, and found that HDAC7 expression was associated with poor prognosis in ovarian cancer patients." (PMID 39431349, 2024). "However, the role and molecular mechanism of HDAC7 underlying the oncogenic function in ovarian cancer have been poorly studied." (PMID 39431349, 2024). "Overall, above data demonstrate that HDAC7 fuels ovarian cancer progression by regulating the AKT/mTOR pathway." (PMID 39431349, 2024). "Collectively, these data provide strong evidences and new sights that HDAC7 controls ovarian cancer cell proliferation and invasion by regulating AKT/mTOR pathway." (PMID 39431349, 2024). "Here, we reasoned to explored the function of HDAC7 in ovarian cancer progression and found that inhibition of HDAC7 obviously cut down p‐AKT and p‐mTOR phosphorylation levels and induced a low rate of cell proliferation and invasion." (PMID 39431349, 2024). "The results suggested that depletion of HDAC7 in human ovarian cancer cells significantly inhibited invasion of OVCAR‐3 and ES2 cells." (PMID 39431349, 2024). "Here, we found that HDAC7 is highly expressed in ovarian cancer and positively correlated with invasion and poor prognosis." (PMID 39431349, 2024). "What's more, mutant activation of AKT was generated in a context of HDAC7 inhibition to fully demonstrate that HDAC7 promotes the malignant progression of ovarian cancer through the AKT/mTOR pathway." (PMID 39431349, 2024). "In the present study, we have investigated the key role of HDAC7 in ovarian cancer cell proliferation, colony formation." (PMID 39431349, 2024). "Taken together, these novel findings suggested that inhibition of HDAC7 suppressed ovarian cancer cell proliferation, colony formation and invasion by reducing phosphorylation levels of AKT/mTOR in vitro." (PMID 39431349, 2024). "Next, we performed transwell assay to explore the role of HDAC7 knockout in regulating invasion of ovarian cancer." (PMID 39431349, 2024). "To further clarify that HDAC7 promotes ovarian cancer progression via regulating AKT/mTOR signalling, we treated OVCAR‐3 and ES2 cells with MK‐2206 2HCl, an AKT inhibitor and tested the expression pattern of AKT/mTOR‐related proteins such as p‐AKT and p‐mTOR." (PMID 39431349, 2024). "Excitingly, these results suggested that Ectopic expression of HDAC7‐mut can rescue the effects of HDAC7 knockout in ovarian cancer cells in vitro." (PMID 39431349, 2024). "HDAC7 has been shown to maintain breast and ovarian cancer stem cells through regulation of H3K27 acetylation at super-enhancer-associated genes." (PMID 35687133, 2022). "Previous studies have also shown the critical role of HDAC7 in cancer metastasis, e.g. in nasopharyngeal, breast, and ovarian cancer." (PMID 35277183, 2022).
ovarian carcinoma (continued). "In our previous studies, OCCCs showed the highest frequency of HIF-1α, histone deacetylase (HDAC) 6, and HDAC7 compared to other ovarian epithelial cancer." (PMID 30678691, 2019). "This notion is also further supported by recent findings that HDAC7 expression is necessary to maintain breast and ovarian cancer stem cells in human and over-expression of HDAC7 is sufficient to augment the CSC phenotype." (PMID 29126425, 2017). "Mechanistically, HDAC7 enhanced ovarian cancer progression by activating p‐AKT and p‐mTOR." (PMID 39431349, 2024). "We first unmasked that HDAC7 acts as an oncogene in ovarian cancer by promoting AKT/mTOR pathway." (PMID 39431349, 2024). "Interestingly, we also observed that EZH2 protein in platinum resistant tumors was negatively correlated with HDAC7 which is transcriptionally upregulated in ovarian cancer stem cells." (PMID 34140011, 2021). "HDAC7 inhibition significantly suppressed growth and invasion of the ovarian cancer cells in vitro and depressed tumour growth in vivo, suggesting that HDAC7 has a significant contribution in ovarian cancer progression and may function as an oncogenic driver of ovarian cancer." (PMID 39431349, 2024). "In addition, this study revealed that HDAC7 promotes ovarian cancer cell proliferation and invasion by augmenting the phosphorylation of AKT/mTOR and HDAC7 expression is positively correlated with poor prognosis." (PMID 39431349, 2024).
acute lymphoblastic leukemia (10 papers, 2015 to 2025). Leukemia with an acute onset, characterized by the presence of lymphoblasts in the bone marrow and the peripheral blood. "High HDAC7 expression was associated with poor prognosis of 74 children with B-lineage CD10-positive acute lymphoblastic leukemia (ALL) (≥95% common-ALL/pre-B ALL)." (PMID 29126425, 2017). "Low levels of HDAC7 expression were reported in the bone marrow of patients with pro‐B acute lymphoblastic leukaemia compared to those from healthy controls, as well as in various malignant B cell lines." (PMID 35303381, 2023). "Interestingly, HDAC7 was overexpressed in patients with both acute and chronic lymphoblastic leukaemia, and its expression correlated with a poorer prognosis in both young and adult patients." (PMID 35303381, 2023). "However, it has also been reported that HDAC7 promotes apoptosis in B acute lymphoblastic leukemia, which is contradictory to our findings." (PMID 34888496, 2021). "Likewise, low HDAC3, HDAC7 and HDAC9 expressions has been associated with poor prognosis and survival in childhood acute lymphoblastic leukemia (ALL)." (PMID 33024443, 2020). "We recently identified HDAC7 to be a novel biomarker and prognostic factor in infants (<1-year-olds) with pro-B acute lymphoblastic leukemia (pro-B-ALL) and MLL-AF4 rearrangement." (PMID 35904805, 2022). "In childhood acute lymphoblastic leukemia (ALL), high HDAC3 expression has been associated with a better prognosis, whereas overexpression of HDAC7 and 9 have been associated with a poorer prognosis." (PMID 26124919, 2015). "Here we report that histone deacetylase 7 (HDAC7) is underexpressed in pro-B acute lymphoblastic leukemia (pro-B-ALL) and Burkitt lymphoma." (PMID 25675295, 2015). "Here, our data showed that HDAC7 is overexpressed in both breakpoint cluster region-Abelson 1 fusion gene-negative (BCR-ABL1−) and BCR-ABL1+ B cell acute lymphoblastic leukemia (B-ALL) cells when compared to normal BM samples." (PMID 32913188, 2020). "Histone deacetylase 7 (HDAC7), a member of class IIa HDACs, has been described to be an important regulator for B cell development and has a potential role in B cell acute lymphoblastic leukemia (B-ALL)." (PMID 32913188, 2020).
colorectal cancer (10 papers, 2006 to 2026). A primary or metastatic malignant neoplasm that affects the colon or rectum. "Multiple studies have linked HDAC7 to colorectal cancer (CRC), which results from the accumulation of both genetic and epigenetic aberrations." (PMID 35303381, 2023). "HDAC7 expression is up-regulated in malignant glioma, colorectal cancer, choroidal melanoma and other diseases." (PMID 38167011, 2024). "The dysregulation of HDAC7 in pancreatic adenocarcinomas, gastric cancers and colorectal cancer makes it a potential biomarker for progression of these cancers." (PMID 35303381, 2023). "Several miRNAs, such as miR-34a16 and miR-48943, suppress HDAC7 expression by targeting HDAC7 mRNA degradation in the breast and colorectal cancer cells respectively." (PMID 32376822, 2020). "Here, we establish HDAC7 as a key epigenetic regulator in colorectal cancer (CRC)." (PMID 42157949, 2026). "Second, in colorectal cancer (CRC), HOXB-AS4 competes with HDAC7 to bind miR-140-5p, thereby promoting the proliferation and migration of CRC cells through the ceRNA regulatory network pathway." (PMID 40657360, 2025).
glioblastoma (10 papers, 2008 to 2024). The most malignant astrocytic tumor (WHO grade IV). "Analysis of genomic data from 154 patients with glioblastoma multiforme has determined a strong correlation between HDAC7 expression and patient outcomes: Subgroup of patients with overexpressed HDAC7 has particularly poor clinical outcomes." (PMID 38167011, 2024). "It has been reported that silencing HDAC7 in glioblastoma (GMB) cell U87 enhanced STAT3 phosphorylation by upregulating JAK1 expression." (PMID 29126425, 2017). "For class II, the highest median was 61.51 (HDAC9b in normal brain) and the lowest was 0.56 (HDAC7 in glioblastoma)." (PMID 18713462, 2008). "It is indicated that HDAC4 has a better prognosis, while, accordingly, HAT1, HDAC1, HDAC3 and HDAC7 may have a poor prognosis for glioblastoma." (PMID 39068393, 2024). "FBXW7 facilitates apoptosis of glioblastoma cells through the ubiquitination and proteolysis of histone deacetylase 7 (HDAC7), which localizes to the inner membrane of mitochondria and will be released into and sequestered within the cytoplasm in response to the initiation of apoptotic cascades." (PMID 35515121, 2022). "Finally, when we compared glioblastoma with normal brain, 7 of 8 genes studied, with the exception of HDAC7, were expressed at lower levels in glioblastoma." (PMID 18713462, 2008). "Overall, these results highlight HDAC7 may be as a promising target in glioblastoma." (PMID 39068393, 2024). "Furthermore, five histone acetylation regulators were selected to be considered as the significant glioblastoma prognosis genes, in which HDAC1, HDAC3, HDAC4 and HDAC7 belong to histone deacetylases differently, HAT1 is a histone acetylase." (PMID 39068393, 2024).
pancreatic cancer (9 papers, 2013 to 2024). "HDAC7 mRNA levels in tumour tissues from patients with pancreatic adenocarcinomas (PA), the most common type of pancreatic cancer, were significantly elevated compared with normal/benign pancreatic tissues or chronic pancreatitis patient tissues." (PMID 35303381, 2023). "In the present study, high levels of HDAC7 mRNA and protein were detected in pancreatic cancer cells." (PMID 28134290, 2017). "With more investigations, the involvement of HDAC7/HDAC2/Nur77 in the pathogenesis of pancreatic tumors can be clarified." (PMID 25275504, 2014). "Furthermore, shRNA‐mediated downregulation of HDAC7 reduced cell growth of a human pancreatic tumour cell line." (PMID 35303381, 2023). "Additionally, Class IIa members, HDAC-5 and -9, have been found to correlate with poor survival rates in medulloblastoma cases, while HDAC-7 overexpression has been related to significantly higher number of deaths and recurrences in pancreatic cancer." (PMID 33799478, 2021). "Interestingly, overexpression of HDAC7 has been demonstrated in pancreatic cancer and suggested as clinical biomarker for pancreatic cancer diagnosis and prognosis." (PMID 31247937, 2019). "The inhibitory effect of our novel compound on HDAC7 in pancreatic cancer cells was considerable." (PMID 28134290, 2017). "It is likely that the HDAC7 in pancreatic cancer could use the VEGF-PKD-HDAC7 axis in the settings of vascular disorders and could explain the potential metastatic of pancreatic cancer." (PMID 25275504, 2014). "We also evaluate by using an in vitro model system of human pancreatic tumor cell line whether HDAC7 knockdown may affect the cell behavior." (PMID 25275504, 2014). "HDAC1 and HDAC7 are increased in human pancreatic tumors compared to normal tissue." (PMID 23696899, 2013). "Moreover, we have evaluated by using an in vitro model system of human pancreatic tumor cell line whether HDAC7 knockdown may affect the cell behavior." (PMID 25275504, 2014). "We also performed a Kaplan-Meier survival analysis, which revealed that the higher expression of HDAC1, HDAC2, HDAC7, and HDAC9 led to poor overall survival in pancreatic cancer patients." (PMID 39123441, 2024). "High levels of cytoplasmic HDAC7 have been reported in pancreatic cancer patients and, in children with ALL, overexpression of HDAC7 and HDAC9 correlated with poor prognosis." (PMID 25915736, 2015). "HDAC IIa composes of HDAC4, HDAC5, HDAC7, and HDAC9, numbers of studies demonstrated HDAC IIa inhibition as an alternative approach to avoid the progression of various diseases, examples like breast tumors, pancreatic cancer, multiple myeloma, and type 2 diabetes." (PMID 35492337, 2022).
gastric cancer (8 papers, 2017 to 2025). A primary or metastatic malignant neoplasm involving the stomach. "HDAC7 expression is dysregulated in many cancers, and high HDAC7 level was associated with poor prognosis of lung and gastric cancers." (PMID 36163081, 2022). "Other protein kinases that were reported to phosphorylate HDAC7 include PKD2 in human gastric cancer cells, PKD1 and PKD3 in B cells and liver kinase B1‐dependent AMP‐activated protein kinase in liver." (PMID 35303381, 2023). "MiR-489 targets HDAC7 to suppress the development of gastric cancer through the PI3K/AKT pathway." (PMID 38955795, 2024). "Moreover, overexpression of HDAC7 is correlated with poor prognosis in gastric cancer and hematological malignancies." (PMID 35277183, 2022).